RNU6-320P (RNA, U6 small nuclear 320, pseudogene)
Gene: Small nuclear RNA gene on chromosome X (136,583,240 to 136,583,345, forward strand). Ensembl gene ENSG00000252320.
Homologues: Orthologues: chimpanzee U6 (99% identical), macaque U6 (92% identical), pig U6 (76% identical), dog U6 (68% identical). Paralogues in human: RNU6-1209P (84% identical), RNU6-797P (84% identical), RNU6-1287P (83% identical), RNU6-130P (83% identical), RNU6-1159P (82% identical), RNU6-115P (82% identical), RNU6-1340P (82% identical), RNU6-1047P (81% identical), RNU6-1083P (81% identical), RNU6-1094P (81% identical), RNU6-1123P (81% identical), RNU6-11P (81% identical), and 1287 more.